ESR1 (estrogen receptor 1)
Diseases named in the same sentence as ESR1 in open-access papers (continued):
Sharing a sentence is not in itself a finding about the gene and the disease.
breast cancer (continued). "Thus, their interaction with cancer related axes including FOXM1/GATA3/FOXA1/ESR1 axis might affect the course of breast cancer." (PMID 34094972, 2021). "For instance, TNBC patients bearing mutations in PIK3CA, AKT1, and ESR1, as well as EGFR amplifications, may be treated with different drugs to those that are used to treat other subtypes of breast cancer (BRCA) and Non-Small Cell Lung Cancer (NSCLS), respectively." (PMID 34680239, 2021). "Finally, an ESR1-mediated miRNA-mRNA network in ERα positive breast cancer were established." (PMID 32500028, 2020). "Interestingly in our study, DIO-fed mice tended and tumor bearing control diet-fed mice had significantly decreased expression of ESR1 on NK cells, suggesting a direct regulation of NK cells via increased estrogen levels in postmenopausal breast cancer and obesity." (PMID 33244094, 2020). "Neo-tanshinlactone, a natural product isolated from S. miltiorrhiza, could selectively inhibit the proliferation of estrogen receptor–positive breast cancer cells by inhibiting the synthesis of ESR1 mRNA and down-regulating the transcription of estrogen receptor α." (PMID 32265690, 2020). "Recent studies have verified tissues ESR1 mutations in most tumor patients, especially with metastatic breast cancer, and some of them to activate the estrogen‐independent receptor, whereas ESR1 and ESR2 expression not only express in breast cancer but also have been shown in other cancer types." (PMID 32536040, 2020). "Other genes, such as ESR1 (logFC 6.02); GATA3 (logFC 3.88); ERBB4 (logFC 3.0); AR (logFC 2.94); CCDC170 (logFC 2.79); MAPT (logFC 2.45); PGR (logFC 2.91); PIP (logFC 5.42) in immunoglobulin G-binding protein from this cluster were closely associated with breast cancer progression." (PMID 32182819, 2020). "Indeed, promoter methylation of ESR-1 (ERα) is common in breast cancer." (PMID 33329395, 2020). "Notably, the transcriptional levels of ESR1 are significantly decreased in relapsed lesions compared with primary tissues in tamoxifen‐treated breast cancer, suggesting that ESR1 might be transcriptionally repressed during acquired resistance to tamoxifen." (PMID 31657150, 2019). "We further demonstrated that FOXA1 could be related to the ESR1 pathway in breast cancer." (PMID 31562808, 2019). "Additional analysis from precancerous ductal and lobular carcinoma in situ (DCIS and LCIS) breast tumors showed over one-third of these samples also harbored ESR1 amplifications suggesting that ESR1 amplifications present in early-stage breast cancer may drive disease progression." (PMID 31106278, 2019). "Additionally, we identified the alterations of epigenetic targets, such as SWI/SNF related genes (SMARCA2, SMARCA4, SMARCA5) or histone modifiers (KMT2C or KMT2D), breast cancer-associated oncogenes (MYCN or MAPKs), or genes that are involved in drug-resistance (ESR1 and PIK3CA/B)." (PMID 31216647, 2019).
breast cancer (continued). "This can most likely be explained by the fact that none of the Wilkerson subtypes have (yet) been associated with a driver event, unlike breast cancer where ESR1 and ERBB2 have been identified as strong drivers giving rise to specific subtypes of breast cancer." (PMID 30379847, 2018). "Comparing the ESR1 gene expression in T47D breast cancer cells and a derived clone selected for its low PR expression (T47D-Y), as previously observed, we confirmed that low PR expression is accompanied by a low expression of ESR1 at both the transcript and protein levels." (PMID 30301163, 2018). "Finally, we assayed a metastatic breast cancer mutation/amplification database and found that the ESR1 LBD mutations were not present in patients with mutations in either KMT2C or KMT2D genes." (PMID 29748621, 2018). "The MBS output showed that ESR1, transcription factor and proto-oncogene frequently overexpressed in breast cancer, is the only mRNA that interacts with hsa-miR-448, hsa-miR-661, and hsa-miR-124-3 for the probabilistic dependency on breast cancer molecular subtype." (PMID 28793339, 2017). "In particular, these graphs have been generated using the Estrogen Receptor 1 (ESR1) as seed gene, which a key regulator for the physiological growth and differentiation of the mammary gland, but also a key element for the malignant progression of breast cancer." (PMID 27895661, 2016). "Single nucleotide polymorphisms (SNPs) in the estrogen receptor 1 (ESR1) and cytochrome P450 19A1 (CYP19A1) genes have been associated with breast cancer risk, endocrine therapy response and side effects, mainly in postmenopausal women with early breast cancer." (PMID 27825388, 2016). "Importantly, the ESR1-responsive enhancer hypermethylation events identified in the endocrine-resistant cell lines were also differentially methylated in endocrine-sensitive and endocrine-resistant breast cancer patient samples." (PMID 26169690, 2015). "Recent preclinical data on the efficacy of an ER degrading agent with a CDK4/6 inhibitor in ESR1-mutant breast cancer provides further rationale for this population, because improvements in TTP or OS could be caused by suppression of ESR1-mutant AI-resistant clones." (PMID 26371134, 2015). "A previous study from our group indicated that regions of DNA methylation variability (MVRs) exist across the ESR1 gene in peripheral blood cells from breast cancer patients compared to healthy matched controls, but the functional implications of this variability remains unknown." (PMID 25927974, 2015). "In addition, transformation of human EpCAM+/CD10−/CD49f + luminal progenitors derived from reduction mammoplasties established tumors with features similar to basal-like breast cancer, including reduced ESR1 and greater K14 expression than tumors derived from differentiated luminal cells." (PMID 26429062, 2015). "Furthermore, in the PPI partners co-identified with the surrogate genes, ESR1 (estrogen receptor 1) is a widely known therapeutic target (for selective modulators, e.g. Raloxifene, Tamoxifen, etc.)in breast cancer in female; however, its roles in the prostate cancer in male have not been revealed." (PMID 25151146, 2014). "Finally, according to the discussion from docking, interaction, and variation, we suggest that S-allylmercaptocysteine might be the best compound to inhibit ESR1 against breast cancer, even better than the control." (PMID 25054138, 2014).
breast cancer (continued). "Consistent with the finding above, the association between breast cancer progression (indicated by OS) and ERE-associated SNP at 21q22.3 (that is, rs1078272) was more significant in patients harboring specific genotypes of a SNP (rs985694) of ESR1, the gene encoding ERα." (PMID 25298020, 2014). "Thus, ESR1 expression may depend on an open chromatin environment at the distal enhancer in addition to the promoter, and therapies that convert the distal region to a closed state can significantly impact ERα status in breast cancer cells." (PMID 24339902, 2013). "Since ESR1, ESR2 and PGR impact the fuction of estrogen and progesterone, we hypothesized that the presence of functional polymorphisms in these genes would be associated with MS-AEs among postmenopausal breast cancer survivors on AI therapy." (PMID 23894347, 2013). "An understanding of the mechanisms underlying the different lifestyle factors associated with breast cancer in rs2046210 and rs3757318 risk allele and non-risk allele carriers may clarify the effects of these SNPs located near ESR1." (PMID 24289300, 2013). "Our analysis of a breast cancer dataset finds that the positive feedback loops across 7 genes, AR, ESR1, MYC, E2F2, PGR, BCL2 and CCND1 are conserved across the basal/triple negative subtypes in multiple datasets that could potentially explain the aggressive nature of this cancer subtype." (PMID 23368093, 2013). "Moreover, functional assays suggest that ESR1 IVS1-397C>T polymorphism affects a binding site for the myb family of transcription factors and the polymorphism has also been studied in various breast cancer association studies." (PMID 22808109, 2012). "Our results provide strong evidence to support that the common polymorphism near the ESR1 gene, rs2046210, is associated with an increased risk of breast cancer in Asian and European populations but not in Africans, although the biological mechanisms need to be further investigated." (PMID 23272245, 2012). "Our findings are consistent with this speculation, and the association between high-risk genotypes of rs12539530 and an increased breast cancer risk was significant in only one subset of women carrying specific genotypes of ESR1, but not in the other subset." (PMID 21281495, 2011). "Therefore, the suppression of NCOA3 that results in inhibition of estrogen-induced degradation of ESR1, but not degradation induced by fulvestrant or GW5638, could have additional clinical effects for ESR1-positive breast cancer." (PMID 19007432, 2008). "In the breast cancer liquid biopsies that were positive for CAPItello-defined PIK3CA, AKT1, or PTEN alterations, the most frequently observed ESR1 alterations (> 10.0%) were D538G and Y537S." (PMID 40597213, 2025). "Imlunestrant (LY3484356), developed by Loxo Oncology at Eli Lilly Corp., is a next-generation brain-penetrant, oral selective ERα degrader that exhibits potent activity in both ESR1 wild-type and mutant breast cancers." (PMID 40641933, 2025). "Genetic correlation analysis revealed significant positive correlations between USP30 expression and ESR1 (estrogen receptor alpha) and PGR (progesterone receptor) levels in breast cancer samples." (PMID 41306556, 2025). "Accordingly, in a study using high-performance liquid chromatography (HPLC), the presentation of ESR1 and ESR1mut peptides on human MHC was shown in an ER+ breast cancer subject along with the presence of human T cells that were reactive to ESR1mut epitopes." (PMID 40244377, 2025). "In the PPI network of 308 genes, several hub genes (ESR1, BRCA1, CREBBP, ERBB2, and LCK) are known to play critical roles in breast cancer development." (PMID 39888956, 2025).
breast cancer (continued). "The downregulated genes (ESR1, AR, SPDEF, and FOXA1) participate in hormone receptor signaling and epithelial integrity in breast cancer." (PMID 41462902, 2025). "In breast cancer, ZMIZ1 enhances ESR1-dependent expression of E2F2, correlating with poor patient outcomes." (PMID 41321319, 2025). "On the contrary, overexpression of ESR1 in breast cancer cells reversed the beneficial effects of SSD on cell apoptosis, as cell apoptosis was significantly reduced upon ESR1 overexpression (p < 0.01)." (PMID 40708058, 2025). "E2, as well as ESR1 expression, was positively correlated with AREG expression in breast cancer models." (PMID 40422206, 2025). "All 6 patients with an ESR1 alteration of the full cohort had HR+ and HER2- breast cancer, representing 21% of the HR+/HER2- subgroup." (PMID 39839709, 2025). "The upregulated differentially expressed breast cancer stem cell markers included CD56/NCAM1, POU5F1, PROCR/CD201, ITGA6, and the downregulated were ESR1, PGR, HER2/ERBB2, ABCG2, CD44, CD24, EPCAM, and CDH1." (PMID 40690373, 2025). "Researchers have also used multiplex ddPCR to detect common gene indicators in breast cancer, achieving highly consistent results with immunohistochemistry (IHC) detection by simultaneously detecting HER2, ESR1, PUM1, and PGR genes." (PMID 40042093, 2025). "Both in vivo and in vitro tests show that TET2 and FOXP1 complex promotes the demethylation of ESR1, GATA3, and FOXA1, which are usually silenced in advanced breast cancer." (PMID 40014756, 2025). "The gene detection results demonstrated elevated levels of breast cancer-related genes, including AZGP1, GATA-3, KRT14, XIST, and ESR1." (PMID 40474021, 2025). "The results revealed elevated levels of several breast cancer-related genes, including AZGP1, GATA-3, KRT14, XIST, and ESR1." (PMID 40474021, 2025). "The data in showed a significant positive correlation between LURAP1L-AS1 and ESR1 expression in breast cancer patients (r = 0.169, p = 1.58 × 10−8), underscoring LURAP1L-AS1 as a clinically relevant marker in ER+ breast cancer." (PMID 39995981, 2025). "For example, in MCF-7 cells, integrated miRNA–mRNA–lncRNA analysis identified a miR-19a–(ESR1/FMNL2/CD74)–DLEU1 axis that potentially modulates metastasis and immunity-related pathways in breast cancer." (PMID 41163216, 2025). "For example, ESR1::CCDC170 has been detected in 6%–8% of Luminal B breast cancers, a more aggressive and endocrine-resistant subtype of HR+/HER2‒ breast cancer, and has been shown to promote increased tumor invasiveness and endocrine resistance." (PMID 41213951, 2025). "In breast cancer, EMT can lead to methylation of ESR1 via a SNAI2–DNMT3B complex, decreasing ER expression and promoting a phenotype with an unfavorable prognosis." (PMID 39941808, 2025). "Research indicated that the transcriptional regulatory network involving estrogen receptors alpha (ESR1), GATA3, and FOXA1 plays a significant role in the development of breast cancer." (PMID 40003882, 2025). "Here we probe if the transcription factor CTCF plays a role in the differential expression of ESR1 in the breast cancer cell lines MCF-7 (ESR1+) and MDA-MB-231 (ESR1-)." (PMID 38236307, 2024). "GWASs have also demonstrated a genetic overlap between UL and breast cancer, particularly in the ER+ subtype, as well as with endometriosis, involving genes such as WNT4/CDC42, GREB1, ESR1, and follicle-stimulating hormone subunit beta (FSHB)." (PMID 38790186, 2024). "A total of 18 cancer genes including ERBB2/HER2, ATR, ESR1 and MAP3K1 were identified to be LateN-to-EarlyT replicated in BRCA and affected by an APOBEC3-mediated omikli event in at least one tumour in the breast cancer cohort." (PMID 39019871, 2024).
breast cancer (continued). "When the correlation was made between ESR1 and IL6ST gene expression, they were positive in all breast invasive carcinoma subtypes, i.e., positive for Basal, Her2, Luminal A, and Luminal B breast cancer patients." (PMID 39201290, 2024). "In ER-positive breast cancer, FOAX1 is an oncogene, whereas in basal breast cancer, the role of FOXA1 is determined by ESR1." (PMID 38605023, 2024). "TIMER2.0 was used to estimate the correlations between ESR1, with a purity adjustment, and the expression of CTSD, EGFR, CCND1, and BCL2 in breast cancer subtypes." (PMID 39202273, 2024). "The coding gene ESR1 is a direct target of miR-301a-3p, and this interaction indirectly leads to the downregulation of CTSD expression in breast cancer." (PMID 38611021, 2024). "Subsequently, we performed univariate and multivariate Cox regression analyses on the relationships among KNSTRN, HER2 (ERBB2), ER (ESR1), and Ki67 (MKI67) expression, clinical factors (age, race, and pTNM-stage), and OS in patients with breast cancer." (PMID 38198023, 2024). "Clinical studies in bioinformatics have indicated a positive correlation between ESR1 and either CCND1 or BCL2 gene expression in all breast cancer patients." (PMID 39202273, 2024). "So far, oral SERD efforts for breast cancer have led to the authorization of elacestrant, the first oral SERD approved for treating metastatic, hormone-resistant breast cancer, including ESR1 mutants." (PMID 39767607, 2024). "Mast cells have been shown to induce the expression and activation of ESR1 and its target genes promoting luminal phenotype while concomitantly suppressing the activation of MET in breast cancer using in vivo and in silico models." (PMID 39742369, 2024). "Consequently, the mutants exhibited a heightened biological capacity to invade and metastasize, which may account for the prevalence of ESR1 mutations in metastatic breast cancer but not in early breast cancer." (PMID 39544302, 2024). "In particular, the expression of TWIST1 in MCF7 breast cancer cells induced Vim and Snai2 expression but repressed CDH1 and ESR1 expression." (PMID 38893094, 2024). "According to the findings, MYLK and estrogen receptor gene expression had a positive correlation with ESR1 in patients with Her2 and with ESR2 expression in patients with Luminal A breast cancer." (PMID 39596804, 2024). "We identified a novel combined prognostic value of ESR1 expression and the corresponding estrogen response signaling (EERES score) for breast cancer." (PMID 38582811, 2024). "Another prominent hit was the estrogen receptor ESR1, found to be strongly enriched at unmethylated L1 loci in the MCF-7 breast cancer cell line." (PMID 38309261, 2024). "We observed low expression of ESR-1 in CD4+ T, CD8+ T, and NK cells when compared with the ESR+ breast cancer cell line T47D." (PMID 39078714, 2024). "In sporadic breast cancer cells, the wild BRCA gene is capable of increasing the expression of the coding gene of ER alpha—ESR1—mediated by the activator Oct-1." (PMID 38672654, 2024). "Particularly in MCF7 cells, increased levels of H3K4ac were observed near the promoters of genes such as ESR1 (estrogen receptor α), PGR (progesterone receptor) and GREB1 (growth regulation by estrogen in breast cancer 1), an early estrogen-responsive gene." (PMID 39456765, 2024). "Genomic analysis of HER2-enriched breast cancer revealed higher expression of the ERBB3 gene and lower expression of the ESR1 gene compared to the non-HER2-enriched subtype." (PMID 39329990, 2024). "It was noteworthy that ESR1, the estrogen receptor gene, was found as a passenger rather than a driver here, different from the reports that this gene drove ESR-positive breast cancer, such as Luminal A, to acquire resistance to endocrine therapy." (PMID 38666214, 2024).